SERPINA9 (serpin family A member 9)
Description:
Protease inhibitor that inhibits trypsin and trypsin-like serine proteases (in vitro). Inhibits plasmin and thrombin with lower efficiency (in vitro).
Synonyms: GCET1; SERPINA11b
Tractability: Antibody: UniProt places it where antibodies can reach, with medium confidence; UniProt predicts a signal peptide or a membrane-spanning region; its Gene Ontology location is reachable by antibodies, with medium confidence.
Gene: Protein-coding gene on chromosome 14 (94,462,717 to 94,481,125, reverse strand). Ensembl gene ENSG00000170054.
Subcellular location: Secreted (Isoform 1); Cytoplasm (Isoform 2); Cytoplasm (Isoform 3); Cytoplasm (Isoform 4); Cytoplasm (Isoform 5); Cytoplasm (Isoform 6); Membrane (Isoform 7)
Gene Ontology:
Molecular function: serine-type endopeptidase inhibitor activity
Cellular component: cytoplasm; extracellular region; membrane
Genetic constraint (gnomAD): Loss-of-function variants: 34 observed, 26.01 expected, observed/expected ratio (o/e) 1.31, 90% interval 0.99 to 1.73. The upper end of that interval is the gene's LOEUF score, 1.73, which puts it in group 6 of 6, group 1 being the genes least tolerant of losing a copy. Missense variants: 594 observed, 518.01 expected, observed/expected ratio (o/e) 1.15, 90% interval 1.07 to 1.23. Synonymous variants: 233 observed, 208.19 expected, observed/expected ratio (o/e) 1.12, 90% interval 1 to 1.25.
Homologues: Orthologues: chimpanzee SERPINA9 (98% identical), macaque SERPINA9 (92% identical), dog SERPINA9 (72% identical), rabbit SERPINA9 (70% identical), rat Serpina9 (66% identical), guinea pig SERPINA9 (66% identical), mouse Serpina9 (65% identical). Paralogues in human: SERPINA7 (50% identical), SERPINA3 (45% identical), SERPINA4 (45% identical), SERPINA11 (44% identical), SERPINA5 (42% identical), SERPINA6 (41% identical), SERPINA1 (39% identical), SERPINA12 (32% identical), SERPIND1 (31% identical), SERPINB4 (30% identical), SERPINB1 (30% identical), SERPINB3 (30% identical), and 24 more.
Diseases named in the same sentence as SERPINA9 in open-access papers:
SERPINA9 is named in the same sentence as 7 diseases in open-access papers, as found by Europe PMC text mining. Sharing a sentence is not in itself a finding about the gene and the disease. The quoted sentences say what the papers report.
B-cell lymphoma (2 papers, 2023 to 2025). "Top proteins specifically associated with germinal center-derived B-cell lymphoma risk included LSAMP, FDCSP, SERPINA9, CCL21 and CD40LG." (PMID 40894013, 2025).
lung carcinoma (1 paper, 2020). "Our study revealed that the CD20+ B cells in the microenvironment of lung cancers produce a high level of VNN2 and SERPINA9 and directly inhibit the growth of NSCLC cells." (PMID 32580738, 2020).
tumor (1 paper, 2023). "These upregulated genes (Cdkn1a, Eda2r and Phlda3), are known for their role in cell cycle arrest, apoptosis and tumor suppression, while the most downregulated genes (Hba-a2, Serpina9, and Ms4a1) are associated with hemoglobin synthesis, mitochondrial function and B cell differentiation 34–43." (PMID 36604457, 2023).
SERPINA9 also shares sentences with these, for which no sentence is quoted: diffuse large B-cell lymphoma (2 papers); coronary artery disease (1); Ehlers-Danlos syndrome (1); Immunodeficiency (1).